EIF2AK2 (eukaryotic translation initiation factor 2 alpha kinase 2)
Description:
IFN-induced dsRNA-dependent serine/threonine-protein kinase that phosphorylates the alpha subunit of eukaryotic translation initiation factor 2 (EIF2S1/eIF-2-alpha) and plays a key role in the innate immune response to viral infection. Inhibits viral replication via the integrated stress response (ISR): EIF2S1/eIF-2-alpha phosphorylation in response to viral infection converts EIF2S1/eIF-2-alpha in a global protein synthesis inhibitor, resulting to a shutdown of cellular and viral protein synthesis, while concomitantly initiating the preferential translation of ISR-specific mRNAs, such as the transcriptional activator ATF4. Exerts its antiviral activity on a wide range of DNA and RNA viruses including hepatitis C virus (HCV), hepatitis B virus (HBV), measles virus (MV) and herpes simplex virus 1 (HHV-1). In addition to serine/threonine-protein kinase activity, also has tyrosine-protein kinase activity and phosphorylates CDK1 at 'Tyr-4' upon DNA damage, facilitating its ubiquitination and proteasomal degradation. Either as an adapter protein and/or via its kinase activity, can regulate various signaling pathways (p38 MAP kinase, NF-kappa-B and insulin signaling pathways) and transcription factors (JUN, STAT1, STAT3, IRF1, ATF3) involved in the expression of genes encoding pro-inflammatory cytokines and IFNs. Activates the NF-kappa-B pathway via interaction with IKBKB and TRAF family of proteins and activates the p38 MAP kinase pathway via interaction with MAP2K6. Can act as both a positive and negative regulator of the insulin signaling pathway (ISP). Negatively regulates ISP by inducing the inhibitory phosphorylation of insulin receptor substrate 1 (IRS1) at 'Ser-312' and positively regulates ISP via phosphorylation of PPP2R5A which activates FOXO1, which in turn up-regulates the expression of insulin receptor substrate 2 (IRS2). Can regulate NLRP3 inflammasome assembly and the activation of NLRP3, NLRP1, AIM2 and NLRC4 inflammasomes. Plays a role in the regulation of the cytoskeleton by binding to gelsolin (GSN), sequestering the protein in an inactive conformation away from actin (By similarity).
Synonyms: PKR; PRKR; PPP1R83
Tractability: Small molecule: a structure with a bound ligand is known; a high-quality ligand is known; it has a binding pocket of medium quality; it belongs to a druggable protein family. PROTAC: it is named in the literature on targeted protein degradation; UniProt records ubiquitination sites on it; ubiquitination databases record sites on it; its protein half-life has been measured; a small molecule that binds it is known.
Target class: Kinase; Other protein kinase PEK family; Other protein kinase group; Protein Kinase; Other protein kinase PKR; Enzyme
Gene: Protein-coding gene on chromosome 2 (37,099,210 to 37,157,688, reverse strand). Ensembl gene ENSG00000055332.
Subcellular location: Cytoplasm; Nucleus; Cytoplasm, perinuclear region
Subcellular location (Human Protein Atlas): Cytosol
Pathways (Reactome):
Immune System: ISG15 antiviral mechanism; Interferon alpha/beta signaling; PKR-mediated signaling
Disease: Evasion by RSV of host interferon responses; Inhibition of PKR
Metabolism of proteins: SUMOylation of immune response proteins
Gene Ontology:
Molecular function: double-stranded RNA binding; eukaryotic translation initiation factor 2alpha kinase activity; identical protein binding; kinase activity; protein binding; protein kinase activity; protein serine/threonine kinase activity; RNA binding; protein phosphatase regulator activity; ATP binding; non-membrane spanning protein tyrosine kinase activity; protein serine kinase activity; protein tyrosine kinase activity
Biological process: antiviral innate immune response; cellular response to amino acid starvation; defense response to virus; negative regulation of cytoplasmic translation; negative regulation of osteoblast proliferation; negative regulation of translation; negative regulation of viral genome replication; positive regulation of canonical NF-kappaB signal transduction; positive regulation of MAPK cascade; response to interferon-alpha; response to virus; negative regulation of cell population proliferation; positive regulation of chemokine production; positive regulation of cytokine production; positive regulation of non-canonical NF-kappaB signal transduction; positive regulation of stress-activated MAPK cascade; regulation of hematopoietic progenitor cell differentiation; regulation of hematopoietic stem cell differentiation; regulation of hematopoietic stem cell proliferation; regulation of NLRP3 inflammasome complex assembly; regulation of translational initiation
Cellular component: cytoplasm; cytosol; membrane; nucleus; perinuclear region of cytoplasm; nucleoplasm; ribosome
Genetic constraint (gnomAD): Loss-of-function variants: 32 observed, 58.49 expected, observed/expected ratio (o/e) 0.55, 90% interval 0.41 to 0.74. The upper end of that interval is the gene's LOEUF score, 0.74, which puts it in group 3 of 6, group 1 being the genes least tolerant of losing a copy. Missense variants: 491 observed, 573.64 expected, observed/expected ratio (o/e) 0.86, 90% interval 0.79 to 0.92. Synonymous variants: 178 observed, 202.84 expected, observed/expected ratio (o/e) 0.88, 90% interval 0.78 to 0.99.
Homologues: Orthologues: chimpanzee EIF2AK2 (99% identical), macaque EIF2AK2 (81% identical), rabbit EIF2AK2 (66% identical), dog EIF2AK2 (61% identical), pig EIF2AK2 (61% identical), mouse Eif2ak2 (57% identical), rat Eif2ak2 (55% identical), guinea pig EIF2AK2 (53% identical), tropical clawed frog eif2ak2 (34% identical), Drosophila melanogaster Wee1 (17% identical). Paralogues in human: EIF2AK3 (31% identical), EIF2AK4 (30% identical), EIF2AK1 (21% identical), WEE1 (19% identical), WEE2 (17% identical), PKMYT1 (15% identical), STK35 (14% identical), PDIK1L (12% identical).
Diseases named in the same sentence as EIF2AK2 in open-access papers:
EIF2AK2 is named in the same sentence as 225 diseases in open-access papers, as found by Europe PMC text mining. Sharing a sentence is not in itself a finding about the gene and the disease. The quoted sentences say what the papers report.
viral infection (423 papers, 2005 to 2026). "The SPV 010 gene encodes the repressor of eIF2-like protein kinase R. PKR is an enzyme encoded by the EIF2AK2 gene that protects against viral infections." (PMID 29415767, 2018). "Interferon-induced, double-stranded RNA-activated protein kinase (EIF2AK2), activated by viral infections, phosphorylates the eIF2 alpha subunit to inhibit translation and viral replication and plays a key role in inflammasome activation." (PMID 40739239, 2025). "EIF2AK2, commonly known as PKR, is an interferon-induced protein kinase primarily activated by viral infection." (PMID 41406153, 2025). "During viral infection, MDA5 levels are also enhanced by the activation of PKR, which is encoded by the gene EIF2AK2." (PMID 38932231, 2024). "Silencing of PERK eliminated the increase in eIF2α-P, contrary to silencing GCN2 (eIF2AK4) and PKR (eIF2AK2), the kinases that primarily respond to ribosome collisions, amino-acid starvation, and viral infection." (PMID 37609272, 2023). "Among them, EIF2AK2, a key regulator of the innate immune response to viral infection, shows the maximum editing difference between high- and low-risk gliomas." (PMID 35406793, 2022). "ISGs products, including OAS1, OAS2, MX1, ADAR, and EIF2AK2, are major players in innate immune defence against viral infection." (PMID 36016774, 2022). "EIF2AK2 encodes PKR an IFN-induced protein kinase, which mediates the innate immune response to viral infection." (PMID 35406793, 2022). "Eukaryotic translation initiation factor 2 alpha kinase 2 (EIF2AK2, also known as PKR) is a protein kinase activated by viral infection and is required for inflammasome-dependent IL-1β and HMGB1 release by macrophages." (PMID 34759927, 2021). "Eukaryotic translation initiation factor 2 alpha kinase 2, better known as PKR, acts as both a sensor and an effector in the response to viral infections." (PMID 34759908, 2021). "PKR (or EIF2AK2) was initially known as a kinase that is activated by double-stranded RNA (dsRNA) typically activated during viral infection, and blocks the translation of viral mRNAs." (PMID 32722591, 2020). "PKR is a protein kinase, encoded by the EIF2AK2 gene, activated by double-stranded RNA (dsRNA) and introduced to the cells by a viral infection." (PMID 33574894, 2020). "EIF2AK2 is the interferon-induced dsRNA-dependent protein kinase which has a prominent role in the innate immune response to viral infection, apoptosis, cell proliferation, and differentiation." (PMID 31665046, 2019). "The P-bodies are manipulated by the viruses for a productive infection to occur, but they also promote immune responses to the viral infection, e.g., via double-stranded RNA protein kinase (PKR alias EIF2AK2)." (PMID 29866042, 2018). "EIF2AK2 or PKR phosphorylates eIF2α in response to viral infection, thereby blocking translation of viral mRNAs and promoting apoptosis." (PMID 29538447, 2018). "In response to viral infection, induction of the interferon response genes, such as EIF2AK2, can lead to a global arrest of translation and subsequent apoptosis." (PMID 17868458, 2007). "For example, G2/I2 showed hyper-editing of type 1 interferon (IFN) receptors (IFNAR1 and IFNAR2), type 1 IFN-stimulated genes (ISGs) (e.g., EIF2AK2, DDX58/RIG-1, MAVS, TRIM56, and TRIM69) and genes involved in immune responses to viral infection (EIF2AK2, DDX58/RIG-1, MAVS, CASP8, CYCS, and HMGB1)." (PMID 35406793, 2022). "EIF2AK2/PKR is induced by innate immunity/viral infection and nutrient and organelle dysfunction." (PMID 30533021, 2018). "The highest ratio in this set was two-fold and out of the top 10 specificities, 7 were in the Type I interferon signature (IFITM3, MX1, IFI6, IFI44L, ISG15, OAS1, IFIT3) and one encodes a protein that is activated by dsRNA as might be present in a viral infection (EIF2AK2)." (PMID 21366908, 2011).
viral infection (continued). "The ISR is activated in response to many different types of cellular stress (including amino acid starvation and viral infection) and is mediated by four different cellular kinases, EIF2AK1 (HRI), EIF2AK2 (PKR), EIF2AK3 (PERK) and EIF2AK4 (GCN2)." (PMID 39951426, 2025). "The signaling cascade was initiated by EIF2AK2 (PKR, an IFN-induced dsRNA-dependent kinase), which plays a central role in the innate immune response to viral infection." (PMID 39062793, 2024). "Eukaryotic translation initiation factor 2 alpha kinase 2 (EIF2AK2), better known as PKR, plays a key role in the response to viral infections and cellular homeostasis by regulating mRNA translation." (PMID 33911136, 2021). "EIF2AK2 (also named as double-strand RNA-dependent kinase, PKR) responses to various types of stress, including DNA damage, mitochondrial stress, viral infection, growth factor deprivation, cytokines, Toll-like receptor activation and cytotoxic drugs." (PMID 32571260, 2020). "ADAR1 knockdown has also been shown to activate another ISG, protein kinase R (PKR, also known as EIF2AK2), in presence of IFN or a viral infection." (PMID 30585209, 2018). "Heme-regulated inhibitor (HRI, EIF2AK1) and protein kinase R (PKR, EIF2AK2) are activated in erythroid cells by heme deprivation and viral infections, respectively." (PMID 27085088, 2016). "Double-stranded RNA-dependent protein kinase (PKR, also known as EIF2AK2) was originally identified as a first-response protein, which induces cell defense responses upon viral infection." (PMID 25360179, 2014). "In addition to GCN2, there are three other mammalian eIF2α kinases: PERK (EIF2AK3/PEK), PKR (EIF2AK2) and HRI (EIF2AK1), which are activated by endoplasmic reticulum (ER) stress, viral infection, and heme deprivation in reticulocyte cells, respectively." (PMID 31194856, 2019). "In particular, they upregulated transcription of the genes involved in cellular response to viral infection and foreign genetic material, such as RIG-I (DDX58), OAS1, MYD88, RNASEL, PKR (EIF2AK2), as well as interferon-dependent transcription factor STAT and IRF families." (PMID 29986702, 2018). "Mapping the differentially expressed proteins to canonical pathways revealed several interlinked pathways with roles in immune response to viral infection, including the IFN signaling, antigen presentation, virus entry via endocytosis, and the EIF2AK2/PKR-induced IFN and antiviral response pathways." (PMID 28174229, 2017).
breast carcinoma (29 papers, 2007 to 2025). "A number of studies have suggested that the deactivation of EIF2AK2 can suppress tumor growth, while elevated expression of EIF2AK2 increases carcinoma progression in a variety of human cancer, including breast cancer." (PMID 41149035, 2025). "In an analysis of data in TCGA, we found that high levels of EIF2AK2 and PI4K2A gene expression were associated with low overall survival rates in breast cancer patients." (PMID 31554935, 2020). "We found that high levels of EIF2AK2 and PI4K2A gene expression were associated with low overall survival rates in breast cancer patients." (PMID 31554935, 2020). "We evaluated the association between PKR (encoded as EIF2AK2) or PI4K2A gene expression and overall survival in breast cancer patients." (PMID 31554935, 2020). "However, when looking at the correlation between TET2 expression and antiviral response genes in breast cancer patients, a positive correlation was found only for EIF2AK2, MAVS, OTUD4, ABCE1, and RNase L expression levels." (PMID 35351824, 2022). "In breast cancer cells EIF2AK2 was elevated compared to normal breast epithelial cells." (PMID 17868458, 2007). "In human breast tumor tissues, mRNA levels of EIF2Ak2, USP18, DDX58, RBL2, STAT2, PGR, S1000A9, and CCND1 were significantly higher in ER+- than in ER--breast cancer tissues." (PMID 29416786, 2018). "It is interesting to note that the mRNA levels of EIF2AK2 and ANXA1 were significantly higher while those of PGR and CCND1 were significantly lower in two ER-- breast cancer cell lines than in MCF-7 cells." (PMID 29416786, 2018).
melanoma (27 papers, 2007 to 2026). A malignant, usually aggressive tumor composed of atypical, neoplastic melanocytes. "The predictive model created in this work comprises five inflammatory response-related genes: C3AR1, CXCL10, EIF2AK2, EMP3, and ICAM1, all of which are all overexpressed in melanoma tissue and are associated with a poor prognosis." (PMID 35982458, 2022). "For example, an increase in EIF2AK2 expression and activity during tumor progression had been described in melanoma and colorectal cancer." (PMID 17868458, 2007).
influenza (22 papers, 2009 to 2024). An acute viral infection of the respiratory tract, occurring in isolated cases, in epidemics, or in pandemics; it is caused by serologically different strains of viruses (influenzaviruses) designated A, B, and C, has a 3-day incubation period, and usually lasts for 3 to 10 days. "In addition Eif2ak2 knock-out mouse mutants are more susceptible to influenza infections." (PMID 22905720, 2012). "The influenza group’s validation experiment showed significant differences in all six genes (IFI44L, IFI44, RSAD2, IFIT3, EIF2AK2, and IFI27)." (PMID 38601162, 2024). "Similarly, hsa-miR-5003-3p, EP300, Valproic Acid, Influenza, and ELAVL1 have interactive relationships centered around EIF2AK2, while hsa-miR-6893-3p, EP300, Calcitriol, Influenza, and HNRNPA2B1 exhibit interactive relationships centered around OASL." (PMID 38601162, 2024).
Alzheimer disease (20 papers, 2010 to 2025). A progressive, neurodegenerative disease characterized by loss of function and death of nerve cells in several areas of the brain leading to loss of cognitive function such as memory and language. "Variants in EIF2AK2 have been linked to neurodevelopmental and neurodegenerative disorders, and its inhibition has shown promise in improving cognitive deficits in Alzheimer’s disease models, suggesting a potential therapeutic avenue." (PMID 40313968, 2025).
Sepsis (12 papers, 2008 to 2025). Sepsis is defined as life-threatening organ dysfunction caused by a dysregulated host response to infection. "However, the precise molecular mechanism underlying the regulation of EIF2AK2 phosphorylation in sepsis is not well understood." (PMID 27779186, 2016). "Shikonin inhibited EIF2AK2 phosphorylation and caspase-1 activity in PMs obtained from mice subjected to lethal endotoxemia or polymicrobial sepsis." (PMID 27779186, 2016). "For instance, aerobic glycolysis mediated by pyruvate kinase M2 (PKM2) has been shown to promote inflammasome activation in macrophages via EIF2AK2 phosphorylation, exacerbating the release of pro-inflammatory cytokines like IL-1β and HMGB1 in sepsis." (PMID 40755920, 2025). "In sepsis-induced acute kidney injury (AKI), AIM2 expression is significantly upregulated and targeted for activation by the EIF2AK2 protein, thereby driving PANoptosis in renal tubular epithelial cells." (PMID 41583472, 2025).
COVID-19 (11 papers, 2020 to 2025). A disease caused by infection with severe acute respiratory syndrome coronavirus 2. "By searching for DTGs associated with IRGs shared between COVID-19 and IS, we identified eight DEGs interacting with two known databases of drug targets: JAK2, ORM1, RNASE2, TNFSF13B, CYBB, EIF2AK2, CD79B and CAMP." (PMID 36969251, 2023). "Neither EIF2AK2 nor IFN-responsive transcription factors such as STAT1 and STAT2 were expressed within SARS-CoV-2 RNA+ cells from participants who developed severe COVID-19." (PMID 34352228, 2021). "In the gene expression validation experiment for the COVID-19 group, significant differences were viewed between the disease and normal groups for the IFIT3 and IFI27 genes, while no notable distinction was found in the EIF2AK2 gene." (PMID 38601162, 2024).
leukemia (11 papers, 2006 to 2025). A malignant (clonal) hematologic disorder, involving hematopoietic stem cells and characterized by the presence of primitive or atypical myeloid or lymphoid cells in the bone marrow and the blood. "Amongst the re-expressed genes were CDKN2A, EIF2AK2, TNFSF10 and XAFI, all of which are associated with cell cycle inhibition or induction of cell death through increasing caspase activity and the reduction of which are known to be associated with the development of leukemia." (PMID 28881658, 2017).
Parkinson disease (11 papers, 2010 to 2025). A progressive degenerative disorder of the central nervous system characterized by loss of dopamine producing neurons in the substantia nigra and the presence of Lewy bodies in the substantia nigra and locus coeruleus. "EIF2AK2 has also been implicated in the extrastriatal neurodegeneration of Parkinson's disease and Huntington's disease." (PMID 20067632, 2010).